SENP1 (SUMO specific peptidase 1)
Diseases named in the same sentence as SENP1 in open-access papers (continued):
Sharing a sentence is not in itself a finding about the gene and the disease.
cancer (58 papers, 2010 to 2026). A tumor composed of atypical neoplastic, often pleomorphic cells that invade other tissues. "In this regard, SENP1 has sparked a great interest, since it has been solidly implicated in a number of cancer types." (PMID 35887358, 2022). "Since these drugs and the drugs that cause to resistance are applied to cancer treatment, then these two class drugs can use to inhibition of SENP1." (PMID 34276383, 2021). "This study presents evidence of the associations between the expression of SENP1 and cancer immunity." (PMID 34276383, 2021). "These SUMOylation regulators have lower overall average mutation frequencies in 33 types of cancer, although SENP1, SENP5, SENP7, and PIAS3 regulators have higher mutation frequencies." (PMID 33123273, 2020). "Strong SENP1 staining was significantly linked to accelerated cell proliferation as measured by Ki67LI in all cancers (p < 0.0001)." (PMID 26202067, 2015). "Thus, SENP1 overexpression caused mTOR pathway activation, increased cancer stemness, and resistance to the mTOR inhibitor." (PMID 36284084, 2022). "Given that SENP1 overexpression caused increased cancer stemness, we also tested whether SENP1 overexpression caused resistance to drugs that are currently used to treat ccRCC." (PMID 36284084, 2022). "It has been reported that there is an association between SENP1 expression and cancer immunity, suggesting that SENP1 could be used as a cancer immunotherapy target." (PMID 35887358, 2022). "Among SENPs, SENP1 dysregulation is associated with a great variety of cancers." (PMID 35887358, 2022). "Then, SENP1 with intervening in the cell cycle cause cancer." (PMID 34276383, 2021). "Loss of PTEN expression allows for the elevated SENP1 to drive microinvasive carcinoma." (PMID 27852060, 2017). "In HCC, SENP1 was demonstrated to promote hypoxia-induced cancer stemness by deSUMOylating HIF-1α, thereby establishing a positive feedback loop." (PMID 41438340, 2026). "Inhibiting SENP1 upregulates the radiosensitivity of cancer cells, making it a promising target for radiosensitization." (PMID 41303693, 2025). "Existing studies indicate that SUMO specific peptidase 1 (SENP1) plays a crucial role in the development and progression of various malignant tumors through diverse molecular mechanisms." (PMID 38954215, 2025). "It has been demonstrated that knocking out the SENP1 gene or inhibiting SENP1 activity prevents the proliferation, cell cycle progression, invasion, and migration of cancer cells." (PMID 41303693, 2025). "The overexpression of SENP1, which is common in cancer cells, results in a decrease in the amount of sumoylated proteins, but this effect is partially reversed by the administration of Mc." (PMID 41303693, 2025). "This article reviews existing knowledge on the structure and function of natural SENP1 inhibitors, particularly their potential application in cancer therapy, including their capacity to overcome resistance to conventional chemotherapies." (PMID 41303693, 2025). "The article will comprehensively summarize the regulatory mechanism of SENP1 and discuss the research progress of its inhibitors, aiming to provide new ideas for cancer therapy." (PMID 38389923, 2024). "Next, we will summarize the progress of SENP1 inhibitors in this paper, aiming to explore beneficial treatments for cancers." (PMID 38389923, 2024). "Differential gene analysis revealed that SENP1 is differentially expressed in multiple malignancies, such as BRCA and BLCA, and is closely associated with poor prognosis in malignant tumors, such as LIHC and KIRP." (PMID 38822351, 2024). "Compared with the corresponding adjacent non-cancer tissues, the level of SENP1 and RHOU was upregulation in HCC tissues, but AnxA6 level was downregulation." (PMID 38566133, 2024). "Subsequent pan-cancer analysis showed that SENP1 was most highly expressed in AML among all TCGA tumors." (PMID 38822351, 2024).
cancer (continued). "For lung cancer, the mRNA and protein levels of SENP1 both are upregulated in cancer tissues (Wang RT." (PMID 38389923, 2024). "SENP1 has been reported as a promising therapeutic target to overcome drug resistance in a variety of cancers." (PMID 38389923, 2024). "Summarily, SENP1 promotes cancer invasion and metastasis mainly through regulating EMT as well as other signaling pathway." (PMID 38389923, 2024). "Although the specific mechanism needs to be further studied, these data provide the possibility of Bethanidine targeting SENP1 for cancer therapy." (PMID 38389923, 2024). "It has been reported that SENP1 is highly expressed and plays a carcinogenic role in various cancers." (PMID 38389923, 2024). "Discussion: Because these compounds can inhibit SENP1 activity, then they can be novel candidates for cancer treatment." (PMID 37502217, 2023). "Momordin Ic(MI), an emerging SENP1 inhibitor, can act as an anti-cancer drug by inhibiting the de-SUMOylation of c-Myc and reducing the level of c-Myc protein, which lead to cell cycle arrest and apoptosis of tumor cells." (PMID 37777749, 2023). "Previously, we studied some secondary metabolites and observed their effects on SENP1 protein in various cancer cell lines and nervous system cells." (PMID 37502217, 2023). "In the previous studies, we showed GA can inhibit SENP1 and can be explored as a drug for cancer treatment and Bethanidine with SENP1 inhibition can be a suitable candidate against cardiovascular diseases." (PMID 35431915, 2022). "Meanwhile, high positive rate of CSN5, GATA1 and ZEB1 in cancer tissues detected by immunohistochemistry and we showed that expression of SENP1 is positively correlated with expression of CSN5, GATA1, ZEB1 in our TNBC samples." (PMID 35342335, 2022). "SENP1 also shows high correlation with sensitivity and resistance to anti-cancer drug and drug targeted genes." (PMID 35887358, 2022). "SENP1 is known to desumoylate and activate several proteins involved in promoting growth, migration, and evasion of cancer cells, like c-JUN, PIN1 and GLI1, among others." (PMID 35887358, 2022). "On the other hand, SENP1 has been shown to desumoylate MYC in cancer tissues, which can be suppressed by Momordin Ic (MI), resulting in cell cycle arrest and apoptosis in CRC cells." (PMID 35887358, 2022). "We used expression vectors that downregulate or overexpress SENP1 to study the role of SENP1 in TNBC cancer cell lines." (PMID 35342335, 2022). "SENP1 is essential for cancer cell growth and proliferation and its knockdown arrests cell cycle and cell proliferation in different human cancer cell lines." (PMID 35465332, 2022). "Previous studies highlight the involvement of SENP1 in adipocytes and cancer cells, but the specific functions of SENP1 in human ADSCs remain poorly defined." (PMID 33371766, 2021). "In the next step to more study and the survey of SENP1 function during cancer, we explored the correlation between expression of five common genes and SENP1 with activation or inhibition of signaling pathways." (PMID 34276383, 2021). "Due to the significance of SENP1 in cancer, we explored transcription factors and miRNAs that regulate SENP1." (PMID 34276383, 2021). "Although SENP1 is overexpressed in many cancer types and is critical for cellular pathways, how SENP1 is regulated in cells is poorly understood." (PMID 33795649, 2021). "In this study, we provided evidence of gene expression, survival status, immune infiltration, transcription factors and miRNAs, pharmacogenomics, and relevant cellular pathway for SENP1 as a biomarker in cancer across the Pan-Cancer cohort." (PMID 34276383, 2021). "We also exhibited that SENP1 is highly correlated with sensitivity and resistance to anti-cancer drugs and drug-targeted genes across cancer cell lines." (PMID 34276383, 2021).
cancer (continued). "Our results provide a new document about the role of SENP1 in tumorigenesis and new insights into cancer therapy targets." (PMID 34276383, 2021). "SENP1 is now considered as a valid anticancer target, overexpressed in certain cancer (like non-small cell lung and pancreatic cancers) and a promotor of HCC." (PMID 33534099, 2021). "Since, SENP1 is regulated by these TFs, then these can be representative a carcinogenic role of the SENP1 in cancer." (PMID 34276383, 2021). "Sentrin specific-protease 1 (SENP1) is a protein involved in deSUMOylation that is almost overexpressed in cancer." (PMID 34276383, 2021). "The results of the Pathological Stage Plot of GEPIA2 also displayed the correlation between SENP1 expression and the pathological stages of cancers consisting of only ACC (p < 0.0107), KICH (p < 0.013), LIHC (p < 0.0097), and OV (p < 0.000332) (p < 0.05)." (PMID 34276383, 2021). "Previous studies have shown that SENP1 plays an important role in the occurrence and progression of malignant tumors by regulating hypoxia-inducible factor (HIF)-1α." (PMID 33791211, 2021). "The study of expression, functions and molecular mechanisms of SENP1 in carcinogenesis for prognosis and treatment in cancers with abnormal SENP1 expression is significant." (PMID 34276383, 2021). "The deSUMOylation enzyme SENP1 has recently been shown to have a prooncogenic role in cancer; however, our mechanistic understanding of how SENP1 is regulated is limited." (PMID 32093760, 2020). "The increased SENP1 mRNA level was observed in the urine of bladder cancer patients and correlated with cancer recurrence." (PMID 33273928, 2020). "Circuits such as ours that sense SENP1 can be used to reprogram cancer cells to express relevant immunomodulators, or trigger specific cell killing by modifying circuit output in an application-tailored fashion." (PMID 30349044, 2018). "The elevated PTEN serves as the primary PCa barrier in SENP1-Tg mice as reduction of PTEN facilitates micro-invasive cancers in SENP1-Tg mice." (PMID 27852060, 2017). "A number of studies have shown that SENP1 functions as an oncoprotein during tumorigenesis and cancer progression." (PMID 27741516, 2016). "We expect to see if bypassing senescence would promote PIN to cancer in the SENP1 prostate transgenic model." (PMID 27659494, 2016). "Finding a markedly higher fraction of cytoplasmic/nuclear SENP1 staining in cancer as compared to normal prostate suggests that SENP1 becomes upregulated in a fraction of tumors." (PMID 26202067, 2015). "SENP1 immunostaining was detectable in 34.5 % of 9,516 interpretable cancers and considered strong in 7.3 %, moderate in 14.9 % and weak in 12.3 % of cases." (PMID 26202067, 2015). "Although clinical studies are so far lacking, these first attempts emphasize the potential druggability of SENP1 in human cancers." (PMID 26202067, 2015). "Known biological functions of SENP1 are consistent with a role in cancer development and progression." (PMID 26202067, 2015). "A key regulator of HIF-1α SUMOylation under hypoxia in general, including in cancer cells, is SENP1 62,63." (PMID 24634093, 2014). "SENP1 has also been revealed to be involved in the development and progression of several types of cancer." (PMID 24137315, 2013). "The mRNA levels of SENP1 were significantly increased in the cancer tissues when compared with the levels in adjacent normal tissues." (PMID 24137315, 2013). "The compounds with the best SENP1 inhibitory activity were tested against PCa cells (PC-3) to evaluate their ability to inhibit cancer cell growth in vitro, with IC50 values as low as 13.0 μM detected." (PMID 24970135, 2012). "SENP1 in our study was included based on the same theory, since it is known that in certain cancers maintain their telomeres by a telomerase independent mechanism known as alternative lengthening of telomeres (ALT)." (PMID 21106093, 2010).
cancer (continued). "Our findings demonstrate that SENP1 is a key factor promoting cancer stemness in HBV-related HCC and may contribute to HCC recurrence and metastasis after surgery." (PMID 41438340, 2026). "Additionally, a significant and positive correlation was observed between SENP1 expression and cancer stemness, which was also indicated by results of a gene set-enrichment analysis targeting HCC recurrence and embryonic stem cell (ESC) signatures." (PMID 41438340, 2026). "Other studies also suggest that the deregulation of sumoylation in DNA repair proteins, including the inhibition of SENP1 activity, may be a promising new strategy for sensitizing cancer cells to chemotherapy." (PMID 41303693, 2025). "SENP1 is overexpressed in lung cancer, glioma, liver cancer, and other cancers." (PMID 41303693, 2025). "Moreover, Gallic acid has lower toxicity than Mc, indicating that Gallic acid is an ideal SENP1 inhibitor in cancer treatment." (PMID 38389923, 2024). "This study aims to provide theoretical references for cancer therapy by targeting SENP1." (PMID 38389923, 2024). "In recent years, overexpression of SENP1 has been reported in different types of cancers." (PMID 38389923, 2024). "Many researches have showed that SENP1 has prognostic value in various cancers." (PMID 38389923, 2024). "Interestingly, another reported target of Mc is SENP1 (sentrin protease 1), a nuclear localised member of a family of related sentrin proteases that has been suggested as the basis of the anti-cancer activity of Mc." (PMID 39057773, 2024). "Multiple studies have identified that SENP1 plays an important role in cancer stemness." (PMID 38389923, 2024). "In summary, SENP1 promotes drug resistance in various cancers through different molecule mechanism." (PMID 38389923, 2024). "Collectively, these findings clarify that SENP1 is of great value in cancers prognosis." (PMID 38389923, 2024). "In conclusion, SENP1 might play an oncogenic role not only in solid tumor, but also in malignant tumor, which deserves further exploring about the specific mechanism." (PMID 38389923, 2024). "The experimental results have shown the SENP1 protein is involved in cancer." (PMID 37502217, 2023). "Therefore, it is urgent to identify potent molecules that can bind to SENP1, inhibit SENP1, and can ultimately be used to treat cancer." (PMID 37502217, 2023). "SENP1 inhibits apoptosis, and increases angiogenesis, estrogen and androgen receptor transcription and c-Jun transcription factor, proliferation, growth, cell migration, and invasion of cancer." (PMID 37502217, 2023). "According to our results and other results, we hope these compounds, especially resveratrol and ZINC85902334, can effectively treat various and complex diseases, especially cancer, and these compounds can be examined to treat other diseases with the overexpression of SENP1." (PMID 37502217, 2023). "Overexpression of SENP1 has been detected in various types of cancer." (PMID 37502217, 2023). "We therefore asked whether overexpressed MYB correlates in the cancer patient cohorts with higher expression of targets enhanced by 2KR-MYB in K562 similar to the analysis we did with SENP1 expression above." (PMID 37468105, 2023). "Because of the important roles of SENP1 in cancer biology, we sorted the compounds with better properties and more active groups to interact with SENP1, which could be stronger inhibitors for SENP1 and could be proposed as anticancer drugs." (PMID 37502217, 2023). "Therefore, SENP1-mediated c-Myc de-SUMOylation prevents c-Myc proteasome degradation and enhances c-Myc transcriptional activity, while SENP1 knockdown inhibits cancer cell proliferation through the reduction of c-Myc expression." (PMID 35465332, 2022). "In addition to MI, other natural compounds, such as triptolide, together with a number of synthetic molecules, have demonstrated to be effective for SENP1 inhibition in a variety of cancer models." (PMID 35887358, 2022).
cancer (continued). "To investigate whether overexpression of SENP1 increases the stemness of ccRCC cells, we performed a sphere-forming assay that detects the clonogenicity of cancer stem cells." (PMID 36284084, 2022). "Further studies are however required to determine whether SENP1 overexpression in HIF2αhi ccRCC cells also modifies cancer sensitivities to other therapeutic agents used in the clinic." (PMID 36284084, 2022). "Additionally, components of sumoylation/desumoylation processes, such as SUMO E2 (ubc9), SUMO E3 (e.g., PIAS1), or SENPs (e.g., SENP1), are upregulated in various cancer types." (PMID 36284084, 2022). "SENP1 also correlates with immune infiltration, and a variety of transcription factors involved in regulation of apoptosis, proliferation, cell cycle, tumorigenesis, invasion and metastasis are responsible of the increased expression of SENP1 in cancer cells." (PMID 35887358, 2022). "The invasion of these cancer cells was also enhanced by SENP1 expression." (PMID 36284084, 2022). "We concluded promoter DNA methylation cannot control the expression of SENP1 in cancer." (PMID 34276383, 2021). "It is reported that SENP1 participates in the progression of various cancers." (PMID 35782332, 2021). "Such cancer type-dependent differences in the regulation of the SENP1 could be important to the development of therapies that target SENP1." (PMID 34276383, 2021). "This was more verified by the pharmacogenomic data from pharmacoDB and GDSC that SENP1 could widely affect anti-cancer drug sensitivity across TCGA cancer types." (PMID 34276383, 2021). "This study supplies a wide analysis of the SENP1 across The Cancer Genome Atlas (CGA) cancer types." (PMID 34276383, 2021). "The SENP1/HIF-1α positive feedback loop mediates hypoxia-induced stemness in cancer cells." (PMID 33746578, 2021). "Furthermore, SENP1 overexpression was sufficient to induce cancer transformation of the normal prostate gland in mice, confirming its role in prostate carcinogenesis." (PMID 33923236, 2021). "We suggested SENP1 through the effect on cell cycle can result in cancer." (PMID 34276383, 2021). "Anti-SENP1 was regarded as a useful approach for cancer therapy." (PMID 33795649, 2021). "Methylation of SENP1 in 32 cancers were also considered in the DNMIVD." (PMID 34276383, 2021). "Therefore, these FDA-approved drugs can be used alone to treat cancer, which shows they can be applied to treat cancer and to inhibit SENP1." (PMID 34276383, 2021). "We reported additional references for future experimental studies on SENP1 in cancer." (PMID 34276383, 2021). "In the survival analysis, the cancer cases were divided into high-expression and low-expression groups based on the expression levels of SENP1 and the correlation of SENP1 expression with the prognosis of patients of various tumors, principally through the TCGA datasets were explored." (PMID 34276383, 2021). "CD4+ T cells, CD8+ T cells, and macrophages were more key-related immune cells, indicating that SENP1 might be introduced as a potential target for cancer immunotherapy." (PMID 34276383, 2021). "To date, several reports have illustrated the essential roles of SENP1 in cancer research." (PMID 33371766, 2021). "Therefore, the important discovery that UBE2T is deSUMOylated and activated by SENP1 suggests an arresting novel mechanism to promote UBE2T SUMOylation in human cancer." (PMID 31969492, 2020). "SENP1 was shown to have a pro-oncogenic role in many types of cancer." (PMID 27178176, 2016). "In cancers, SENP1 immunostaining was predominantly localized in the nucleus." (PMID 26202067, 2015). "SENP1 expression has strong prognostic impact in a molecularly defined subset of cancers." (PMID 26202067, 2015).